UGDH (UDP-glucose 6-dehydrogenase)
Description:
Catalyzes the formation of UDP-alpha-D-glucuronate, a constituent of complex glycosaminoglycans. Required for the biosynthesis of chondroitin sulfate and heparan sulfate. Required for embryonic development via its role in the biosynthesis of glycosaminoglycans (By similarity). Required for proper brain and neuronal development.
Synonyms: UDP-GlcDH; UDPGDH; GDH; UGD; DEE84; EIEE84
Tractability: Small molecule: a structure with a bound ligand is known; it has a high-quality binding pocket. PROTAC: ubiquitination databases record sites on it; its protein half-life has been measured.
Target class: Enzyme; Oxidoreductase
Gene: Protein-coding gene on chromosome 4 (39,498,755 to 39,528,311, reverse strand). Ensembl gene ENSG00000109814.
Subcellular location (Human Protein Atlas): Nucleoplasm
Pathways (Reactome):
Metabolism: Formation of the active cofactor, UDP-glucuronate
Gene Ontology:
Molecular function: identical protein binding; UDP-glucose 6-dehydrogenase activity; NAD binding; oxidoreductase activity, acting on the CH-OH group of donors, NAD or NADP as acceptor
Biological process: glycosaminoglycan biosynthetic process; neuron development; protein hexamerization; UDP-glucuronate biosynthetic process; chondroitin sulfate proteoglycan biosynthetic process; gastrulation with mouth forming second; heparan sulfate proteoglycan biosynthetic process
Cellular component: extracellular exosome; cytosol; nucleus
Genetic constraint (gnomAD): Loss-of-function variants: 31 observed, 46.37 expected, observed/expected ratio (o/e) 0.67, 90% interval 0.5 to 0.9. The upper end of that interval is the gene's LOEUF score, 0.9, which puts it in group 3 of 6, group 1 being the genes least tolerant of losing a copy. Missense variants: 437 observed, 582.41 expected, observed/expected ratio (o/e) 0.75, 90% interval 0.69 to 0.81. Synonymous variants: 157 observed, 194.17 expected, observed/expected ratio (o/e) 0.81, 90% interval 0.71 to 0.92.
Gene-disease validity (ClinGen):
ClinGen rates the evidence that UGDH causes each of these diseases.
congenital heart disease (autosomal dominant): Disputed. A heart disease that is present at birth.
Homologues: Orthologues: chimpanzee UGDH (100% identical), dog UGDH (99% identical), macaque UGDH (99% identical), pig UGDH (98% identical), rat Ugdh (98% identical), mouse Ugdh (98% identical), guinea pig UGDH (97% identical), rabbit UGDH (96% identical), tropical clawed frog ugdh (88% identical), zebrafish ugdh (85% identical), Drosophila melanogaster sgl (65% identical), Caenorhabditis elegans sqv-4 (62% identical).
Diseases named in the same sentence as UGDH in open-access papers:
UGDH is named in the same sentence as 61 diseases in open-access papers, as found by Europe PMC text mining. Sharing a sentence is not in itself a finding about the gene and the disease. The quoted sentences say what the papers report.
lung carcinoma (11 papers, 2020 to 2025). "This occasional nuclear UGDH enzyme stain was considered pertinent, as other studies have associated nuclear localization of UGDH protein in lung cancer cells with epithelial-to-mesenchymal transition (EMT) and a malignant phenotype." (PMID 36107941, 2022). "Consistent with the previously reported findings in lung cancer cells, UGDH knockdown increased E-cadherin expression in OV90 cells." (PMID 37858159, 2023). "Dysregulated glucuronic acid metabolism including increased UGDH expression, altered UDP‐Glc and UDP‐GlcUA levels have been implicated in the growth and metastasis of multiple tumours, such as breast, ovarian and lung cancers." (PMID 35979621, 2022). "For example, recent work showed that upon activation of EGF receptor, UDP-glucose 6-dehydrogenase (UGDH) is phosphorylated in human lung cancer cells." (PMID 34681726, 2021). "UGDH participates in tumour formation and cancer migration in breast cancer, colorectal carcinoma, glioblastoma and lung cancer." (PMID 32893977, 2020). "In lung cancer, UGDH promotes tumor metastasis by increasing the stability of Snail mRNA." (PMID 33943009, 2021). "It was previously reported that UGDH mediates metastasis and epithelial-mesenchymal transition (EMT) in lung cancer." (PMID 37858159, 2023). "UGDH has been found to be upregulated in epithelial cancers, including BC, highly metastatic ovarian cancer cell lines, GBM, and lung cancer." (PMID 37834160, 2023). "Recently, Wang et al14 found that inhibition of UGDH led to degradation of SNA1 mRNA and impaired lung cancer migration." (PMID 32893977, 2020). "We recently demonstrate that UDP-glucose 6-dehydrogenase (UGDH) enhances the stability of snail family transcriptional repressor 1 (SNAI1) mRNA to initiate the epithelial-mesenchymal transition, thus promoting the extravasation process of lung cancer cells." (PMID 41390768, 2025). "Phosphorylated UGDH interacts with HuR to weaken the UDP-glucose-mediated inhibition of HuR binding to SNAI1 mRNA, thereby enhancing the stability of SNAI1 mRNA, increasing the epithelial-mesenchymal transition of lung cancer cells, and the migration of tumour cells and lung cancer metastasis." (PMID 35664798, 2022).
breast carcinoma (10 papers, 2018 to 2025). "Paradoxically, both fibronectin (Fn1) and Six1, glycoproteins in the extracellular matrix associated with more aggressive breast cancer phenotypes, were upregulated in UGDH KD." (PMID 37769033, 2023). "High UGDH level was associated with worse patient survival in basal breast cancer patients based on KM plotter." (PMID 34942055, 2022). "Of these, UGDH was most prominently altered and has previously been associated with breast cancer patient survival." (PMID 34942055, 2022). "We continued analyzing the possible associations between UGDH expression and the roles of different genes related to tumor progression for the survival prognosis of breast cancer patients by analyzing Kaplan–Meier plots." (PMID 33572239, 2021). "The results obtained allowed us to propose UGDH as a new prognostic marker in breast cancer, positively associated with development of epirubicin resistance and modulation of extracellular matrix." (PMID 33572239, 2021). "In breast cancer models, UGDH knockdown caused increased CDH1 and FN1 expression." (PMID 37858159, 2023). "UGDH activity was implicated to-date in lung adenocarcinoma, breast cancer and glioblastoma." (PMID 36107941, 2022). "In response to EPI, breast cancer cells altered the expression of UGDH, which indicates that it could act as a marker associated with this type of cancer." (PMID 33572239, 2021). "Interestingly, even though the high expression of UGDH was associated with worse survival in basal breast cancer patients and decreased UGDH jeopardized cell proliferation and invasion, all the mesenchymal cells in this study possess upregulated UGDH and are nontumorigenic." (PMID 34942055, 2022). "In some breast cancer subtypes, such as C1 UGDH + subgroup, the activity of oxidative phosphorylation pathway is significantly enhanced, which accelerates the proliferation rate of these cells and promotes the growth and development of tumors." (PMID 40114930, 2025). "To relate these findings to breast cancer, we tested the protein level of UGDH in the tumorigenic breast mesenchymal cell line D492HER2." (PMID 34942055, 2022). "Our results support an unexplored relationship between UGDH and GPC, both of which have previously been independently associated with breast cancer progression." (PMID 34942055, 2022). "We evaluated the effect of silencing the UGDH gene with a specific siRNA on the EPI response using that aggressive breast cancer cell line, by studying cellular processes ranging from cell survival to modulation of extracellular matrix composition." (PMID 33572239, 2021). "We know that further research is needed to confirm these novel findings, but this should support new studies of UGDH in breast cancer and other types of tumors." (PMID 33572239, 2021). "In this process, the role of UGDH is crucial, making it possible to be proposed as a marker of tumor progression during chemotherapy in breast cancer patients." (PMID 33572239, 2021). "Similar results were found when evaluating the expression of UGDH in breast cancer cell lines with different aggressive phenotypes and ER, PR and HER2 status." (PMID 33572239, 2021). "Similar results were found when evaluating the expression of UGDH in patients with breast cancer, according to HER2 status." (PMID 33572239, 2021). "Because these two compounds inhibited the proliferation of MCF-7 human breast cancer cells, it was concluded that gallic acid and quercetin are effective inhibitors of UGDH that exert strong antiproliferative activity in breast cancer cells." (PMID 29713632, 2018). "Thus, while there are demonstrated relationships between UGDH and HA in breast cancer in experimental settings, these relationships are less well studied in clinical practice." (PMID 37769033, 2023). "Both UGDH and HA levels have been connected to reprogramming glucose metabolism in breast cancer." (PMID 37769033, 2023).
breast carcinoma (continued). "Indeed, genetic or pharmacological targeting of UGDH in lung, ovarian and breast cancer models significantly impaired tumour metastasis." (PMID 35979621, 2022). "UGDH knockout attenuates the migration of breast cancer cells in vivo." (PMID 36233276, 2022). "Furthermore, in response to different concentrations of EPI, breast cancer cells altered the expression of UGDH during resistance acquisition, and with dependence on hormonal receptors expression." (PMID 33572239, 2021). "Besides, to extend the study to other in vitro models of breast cancer, we investigated the mRNA expression of UGDH from microarray public databases from four breast cancer cell lines with different aggressiveness and hormone receptors status." (PMID 33572239, 2021). "The results found in both in silico and breast cancer patient studies allowed us to hypothesize that the UGDH enzyme is involved in the progression of triple-negative breast cancer, even in cases that have received chemotherapeutic treatment." (PMID 33572239, 2021). "Besides, we studied the expression of UGDH in breast cancer patients, both in tumors and adjacent normal tissue, and the association of its expression with patient’s survival to propose it as a future prognostic marker." (PMID 33572239, 2021). "Furthermore, in the present study we analyzed the expression of UGDH mRNA in samples obtained from tumors and adjacent normal tissue of breast cancer patients previously characterized according to ER, PR, HER2 and Ki67 status in our laboratory." (PMID 33572239, 2021). "We studied UGDH expression in tumors and adjacent tissue from breast cancer patients." (PMID 33572239, 2021). "First, to have an overview of UGDH expression in different solid tumors, we analyzed its expression in samples from The Cancer Genome Atlas (TCGA), which demonstrated that UGDH is differentially expressed in lung, liver, prostate and breast cancers." (PMID 33572239, 2021). "Since we observed that despite the induction of intracellular accumulation of EPI after UGDH knockdown, it failed to increase apoptosis, we decided to study the modulation of autophagy as a possible mechanism involved in EPI resistance in breast cancer cells transfected with UGDH siRNA." (PMID 33572239, 2021). "Moreover, upregulation of UGDH by estrogen and androgens is known to be present in estrogen-responsive breast cancer cells." (PMID 29713632, 2018). "Additionally, the aim was to determine UGDH as a possible prognosis marker in breast cancer." (PMID 33572239, 2021). "Using siRNA to silence Cul3 in breast cancer cells, microarray analysis revealed that the expressions of oxidative stress downstream genes (AKR1C1, UGDH, TXN, GCL, and NQO1) were overexpressed at least 2-fold." (PMID 35242279, 2022). "This work aimed to evaluate the effect of UGDH knockdown on epirubicin response and hyaluronan metabolism in MDA-MB-231 breast cancer cells." (PMID 33572239, 2021). "In the present study, we analyzed the expression of UGDH mRNA in tumoral (TT) and normal adjacent tissue (NAT) samples obtained from four breast cancer patients previously characterized according to ER, PR, HER2 and Ki67 status in our laboratory." (PMID 33572239, 2021). "Several additional studies in BC have further established that higher levels of UGDH are associated with worse prognoses for patients (particularly those with triple negative breast cancer (TNBC) receiving chemotherapy) and more invasive, metastatic phenotypes in BC samples." (PMID 37769033, 2023). "Further studies on understanding the roles of UGDH on GPC and its relationship with EMT could be valuable in developing novel therapeutics against breast cancer." (PMID 34942055, 2022). "However, the importance of the glucuronidation reaction and the role of the UGDH enzyme in breast cancer treatment have not yet been studied." (PMID 33572239, 2021).
breast carcinoma (continued). "Furthermore, the unexpected increase in HYALs expression considering higher pericellular area could be explained taking into account that, in the absence of UGDH, breast cancer cells require a new source of UDP-GlcUA to synthesize HA (and other GAGs and PGs)." (PMID 33572239, 2021).
developmental epileptic encephalopathy (9 papers, 2020 to 2025). "Fibroblasts derived from patients with developmental epileptic encephalopathy associated with a pathogenic variant in the UDP glucose 6 dehydrogenase (UGDH) gene have shown changes in UGDH stability, oligomerization, and enzymatic activity." (PMID 38637998, 2024). "Other more severe LoF mutations have also been identified in UGDH in humans, causing recessive developmental epileptic encephalopathy." (PMID 33090996, 2020). "Here, the authors report biallelic variants in the gene encoding UDP-Glucose 6-Dehydrogenase (UGDH) in individuals affected by developmental epileptic encephalopathies that impair UGDH stability, oligomerization, or enzymatic activity in vitro." (PMID 32001716, 2020). "Case 18: Decreased expression of the UGDH gene, which is associated with AR Developmental and Epileptic Encephalopathy 84, was identified as an extreme outlier (z-score –4.15, fold change 0.62, p value 7.50e−05) in a male with global developmental delay and epileptic encephalopathy." (PMID 40593860, 2025). "Developmental epileptic encephalopathies are severe disorders characterized by intractable epileptic seizures and developmental delay where UDP-glucose-6-dehydrogenase (UGDH) gene has been implicated as a critical component, responsible for the conversion of UDP-glucose to UDP-glucuronic acid." (PMID 37719765, 2023). "Among them, the RCF1 gene is associated with cerebellar ataxia, vestibular areflexia syndrome, and neuropathy (MIM:614,575), while the UGDH gene was reported in patients affected by developmental and epileptic encephalopathy." (PMID 36833427, 2023).
glioblastoma (6 papers, 2020 to 2023). The most malignant astrocytic tumor (WHO grade IV). "UGDH has been associated with promoting cancers of the lung, glioblastoma, colon, prostate, breast and ovary." (PMID 37858159, 2023). "In glioblastoma cell lines, silencing of UGDH with siRNA reduced viability and migration of cancer cells in vitro and tumor growth in vivo, largely due to the reduction of ECM proteins tenascin and laminin that promote glioblastoma progression." (PMID 37858159, 2023). "Oyinlade et al13 also showed that high expression of UGDH in glioblastoma leads to poor survival rates." (PMID 32893977, 2020). "We did not have a syngeneic model of the C1/MES and C4/DIF subtypes to thoroughly examine immune infiltration in xenografts, but our findings warrant further investigation to explore whether UGDH influences immune infiltration in EOC as was recently described in glioblastoma." (PMID 37858159, 2023). "In glioblastoma, KLF4 methylation-dependent transcriptional activation of UDP-glucose 6-dehydrogenase (UGDH) increases the synthesis of glycosaminoglycans (GAGs), which constitute essential structural polymers/components of the extracellular matrix (ECM), thus facilitating tumor growth and invasion." (PMID 37835497, 2023).
ovarian carcinoma (6 papers, 2020 to 2024). A malignant neoplasm originating from the surface ovarian epithelium. "In conclusion, we found that the up‐regulation of UGDH is related to ovarian cancer metastasis and the deficiency of UGDH leads to the decrease of cell migration, cell invasion, wound healing and cell proliferation ability." (PMID 32893977, 2020). "Thus, loss of UGDH expression contributes to the inhibition of ovarian cancer cell proliferation and cell invasion." (PMID 32893977, 2020). "We identified key subtype-specific differences indicating that UGDH pro-tumorigenic activity predominates in the mesenchymal subtype of HGS ovarian cancer." (PMID 37858159, 2023). "In these ovarian cancer models, knocking down UGDH also decreased the activity of actin as a key migratory protein." (PMID 37769033, 2023). "Knock‐down of UGDH has been reported to downregulate the phosphorylation of ERK (pERK) in highly invasive ovarian cancer cells." (PMID 34942055, 2022). "Our findings reveal that UGDH can serve as a prognostic marker and that the inhibition of UGDH is a promising strategy for ovarian cancer treatment." (PMID 32893977, 2020). "Our results suggest that knockdown of UGDH suppressed the ovarian cancer proliferation rate and induced cell cycle arrest in G0/G1 phase by up‐regulating cell cycle inhibitory proteins." (PMID 32893977, 2020). "Collectively, UGDH can serve as a prognostic marker and a potential therapeutic target for restricting ovarian cancer metastasis." (PMID 32893977, 2020). "To further elucidate the regulatory role of UGDH in cell proliferation, we performed propidium iodide (PI) staining in combination with flow cytometry to analyse the cell cycle distribution in ovarian cancer cells." (PMID 32893977, 2020). "Our immunoblot analysis revealed that cyclin D2 was elevated in UGDH knockdown ovarian cancer cells." (PMID 32893977, 2020). "In the cell line‐based study, we observed overexpression of UGDH in the highly aggressive ovarian cancer cell line." (PMID 32893977, 2020). "In the current study, we observed overexpression of UGDH in highly invasive ovarian cancer cells, and siRNA‐mediated knockdown of UGDH reduced the metastatic abilities of TOV21G, A2780 and HeyA8 cell lines." (PMID 32893977, 2020). "Ovarian cancer cells were transfected with 50 nmol/L of UGDH siRNA for 4 hours and recovered in complete medium for at least 16 hours before analysis." (PMID 32893977, 2020). "By using proteomics approaches, we found that UDP‐glucose dehydrogenase (UGDH) was up‐regulated in highly metastatic ovarian cancer TOV21G cells, characterized by high invasiveness (TOV21GHI), in comparison to its parental control." (PMID 32893977, 2020). "We next focused on the role of UGDH in cell wound healing and cell migration in ovarian cancer by wound healing assay (scratch assay) and transwell migration assay." (PMID 32893977, 2020). "In our study, knockdown of UGDH decreased the phosphorylation of ERK in ovarian cancer cells, suggesting that UGDH is upstream of ERK in the signalling cascade." (PMID 32893977, 2020). "Subsequent analysis revealed overexpression of UGDH in highly invasive ovarian cancer tissue specimens." (PMID 32893977, 2020). "The results revealed that knockdown of UGDH decreased ovarian cancer migration, wound healing ability and cell proliferation." (PMID 32893977, 2020). "In the present study, we investigate the role and detailed mechanism of UGDH activity in ovarian cancer metastasis development." (PMID 32893977, 2020). "To understand the regulatory role of UGDH in ovarian cancer metastasis, we focused on monitoring the molecular pathway of UGDH knockdown in TOV21G cells." (PMID 32893977, 2020). "Our immunoblot analysis revealed decreased expression levels of MMP‐2 and MMP‐9 in UGDH‐silenced ovarian cancer cells, which is consistent with previous reports." (PMID 32893977, 2020).